CSF2RB (colony stimulating factor 2 receptor subunit beta)
Diseases named in the same sentence as CSF2RB in open-access papers (continued):
Sharing a sentence is not in itself a finding about the gene and the disease.
infection (14 papers, 2013 to 2025). The state of being infected such as from the introduction of a foreign agent such as serum, vaccine, antigenic substance or organism. "We inoculated Csf2rb−/− mice using the inhalation route and harvested lungs for analysis throughout infection." (PMID 35587201, 2022). "Similarly, we found that AM were essential for acute clearance of D39 in B6 mice, as evidenced by ~103-fold increased lung CFUs in Csf2rb-/- mice after 105 CFU D39 infection alone." (PMID 37771584, 2023). "Infection with adenovirus-CSF2RB increased CSF2RB protein expression in an MOI-dependent manner." (PMID 37064880, 2023). "To test this hypothesis, we assessed the progression of infections with the WT strain and the mar1Δ mutant strain in the Csf2rb−/− mouse background, which is defective in GM-CSF signaling due to loss of the functional GM-CSF receptor." (PMID 35587201, 2022). "Interestingly, there was also a strong upregulation of GM-CSFR β subunit genes (Csf2rb and Csf2rb2) in the lungs 28 days post- infection in WT mice." (PMID 29872095, 2018). "Recently, however, it has been reported that Csf-2r-deficient (Csf2rb−/−Csf2rb2−/−) mice that lack the common β subunit (Csf2rb) and the IL-3r unique β subunit (Csf2rb2) were equally efficient as WT mice in controlling L. monocytogenes bacterial burden in the spleen and liver early after infection." (PMID 23460827, 2013). "Most of the genes for chemokines/chemokine receptors (CCR2, CCR6, CCR7, CSF2RB, CX3CR1 and CXCR4) and cytokines/cytokines receptors (IL1R2, IL8, IL18, IL20RA and IL22RA2) were down-regulated after infection by vvIBDV at 3 dpi." (PMID 33110122, 2020). "Among these, some became upregulated during the early stage of infection (day 4) CCL7, CXCL11, IL1R1 (cytokine receptor) and IL15RA, and others became upregulated during the late stage of infection (day 7): IL2RA, CSF2RB and others." (PMID 27595844, 2016). "We observed no increase in survival for CSF2RB R461C cells compared to controls (ENU-treated and no infection) or any other transformed cell line, indicating that the CSF2RB R461C mutation is not causing genetic instability." (PMID 28208123, 2017).
cancer (8 papers, 2021 to 2025). A tumor composed of atypical neoplastic, often pleomorphic cells that invade other tissues. "CSF2RB mutations or alterations in signaling pathways and expression can contribute to cancer progression." (PMID 40837403, 2025). "This is the first report of a CSF2RB‐activating somatic mutation in any type of cancer specimen." (PMID 34729943, 2021). "Analyses of the cancer genomics data related to the CSF2RB gene/protein from different databases revealed some striking results that need to be discussed in order to draw the right conclusion from this study." (PMID 40837403, 2025). "In this study, we used genetics screens, analysis of the Cancer Dependency Map, and IP/MS to discover a mechanism of CSF2RB regulation by a STUB1/CHIC2 complex." (PMID 36108743, 2022). "Similar to previous findings, CSF2RB expression was reduced in cancer tissues compared with the adjacent normal tissues (p < 0.05)." (PMID 35574409, 2022). "The CSF2RB gene is expressed in tumors across all cancer types available from the TCGA study." (PMID 40837403, 2025). "Finally, we used Western blot, real-time quantitative PCR (RT-qPCR), and immunohistochemistry (IHC) to validate CSF2RB expression in cancer and para-cancerous tissues." (PMID 35574409, 2022). "Some of the significant cancer hallmark terms are inflammatory response (CD14, CD69, IL10RA), KRAS signaling up (CD37, IL10RA, GPNMB), IL-6/JAK/STAT3 signaling (CD14, CSF2RB), Interferon Gamma Response (CD69, CSF2RB, IL10RA, VCAM1, SLAMF7), TNF-alpha Signaling via NF-kB (CD69)." (PMID 35486660, 2022).
autosomal recessive disease (1 paper, 2026). Autosomal recessive form of disease. "Firstly, the present study was based on molecular investigations of index cases, and for autosomal recessive diseases (e.g., ABCA3, MARS1, CSF2RB), most often concerned the first affected individual in the family." (PMID 41041870, 2026).
blood cancers (1 paper, 2025). "The role of CSF2RB and other similar receptors in hematological or blood cancers was established in recent decades through several scientific research studies using hematological cell lines, primary cells, animal models, and human patients." (PMID 40837403, 2025).
heart (1 paper, 2023). "The present study determined whether CSF2RB modification can enhance the effects of engrafted MSCs in repairing ischemic heart injury and investigated the underlying molecular mechanisms." (PMID 37064880, 2023). "Importantly, CSF2RB overexpression further enhanced the cardioprotective effect of ADSCs against ischemic heart injury." (PMID 37064880, 2023).
CSF2RB also shares sentences with these, for which no sentence is quoted: autoimmune PAP (3 papers); eczema (2); genetic disease (2); multiple sclerosis (2); acute renal failure (1); adenocarcinoma (1); allergic rhinitis (1); Allergy (1); alveolar proteinosis (1); anaemia (1); Anxiety (1); Arrhythmia (1); autism (1); bipolar disorder (1); brain diseases (1); bronchiectasis (1); cervical adenocarcinoma (1); colon adenocarcinoma (1); connective tissue disease (1); diabetes (1); eosinophilia (1); eosinophilic disorders (1); eosinophilic esophagitis (1); esophageal cancer (1); fibrosis (1); hematological cancer (1); hematological malignancies (1); Hepatic steatosis (1); Hypercholesterolaemia (1); hypereosinophilic syndrome (1).
A further 24 diseases each share a sentence with CSF2RB in 1 paper.